GAS5 (growth arrest specific 5)
Diseases named in the same sentence as GAS5 in open-access papers (continued):
Sharing a sentence is not in itself a finding about the gene and the disease.
lung carcinoma (continued). "Taken together, a role for GAS5 in halting the cell cycle as well as promoting cell differentiation in normal cells supports its tumor-suppressive role reported in lung cancer." (PMID 37370745, 2023). "GAS5, a tumor-suppressive lncRNA, plays a role in the sensitization of lung cancer cells to therapy." (PMID 37370745, 2023). "GAS5 has a clear tumor-suppressive role in lung cancer; therefore, these studies are consistent and support the use of GAS5 as biomarker for diagnosis and for responses to clinical intervention." (PMID 37370745, 2023). "The overexpression of GAS5 in lung cancer cells can inhibit proliferation and tube formation in HUVECs in the form of exosomes, thereby affecting angiogenesis." (PMID 37151887, 2023). "In lung cancer, GAS5 was found down-regulated in 72 NSCLC tumor samples as compared to their paired adjacent normal tissues, suggesting a tumor-suppressive role." (PMID 37370745, 2023). "Lung cancer-derived exosome profiles showed reduced expression of GAS5 compared to the exosomes of healthy lung cells." (PMID 36905871, 2023). "Human umbilical vein endothelial cells (HUVECs) are controlled in terms of apoptosis, proliferation, and tube formation by exosomal GAS5 that is generated from lung cancer." (PMID 36362424, 2022). "For instance, by preventing angiogenesis, GAS5 has been shown to be a possible therapeutic target for lung cancer." (PMID 36362424, 2022). "lncRNA has an important role as a competing endogenous RNA (ceRNA) that binds microRNA, and in other cancer models, it was found that GAS5 directly interacts with miR-21, which accounts for radioresistance in lung cancers." (PMID 35059460, 2022). "Studies have found that the expression of lncRNA growth arrest-specific transcript 5 (GAS5) is low in lung cancer tissues compared with adjacent normal tissues." (PMID 35963868, 2022). "Enhancing the expression of lncRNA GAS5 effectively disrupts the proliferation and migration of lung cancer cells via miRNA-205 downregulation and enhancing PTEN expression." (PMID 33670518, 2021). "Another study reports that, GAS5 represses lung cancer cell proliferation and metastasis via regulating miR-205/PTEN axis." (PMID 34022918, 2021). "One of the well-known tumor-suppressing lncRNAs in lung cancer is growth arrest-specific transcript 5 (GAS5)." (PMID 33670518, 2021). "RT-PCR data suggested that GAS5 expression was reduced about 2-folds in lung cancer tissue than that of the normal group." (PMID 33976738, 2021). "In contrast, both EGFR‐mutated lung cancer cells NCI‐H1975 and HCC827 had higher expression levels for LncRNA GAS5." (PMID 33433063, 2021). "GAS5 overexpression significantly inhibited lung cancer cell proliferation by increasing the E-cadherin and decreasing N-cadherin." (PMID 33976738, 2021). "In summary, this study has proved that GAS5 was closely related to epigenetic regulation of lung cancer." (PMID 33976738, 2021). "Here, it is proved that GAS5 was closely related to cell apoptosis, and its down-regulated expression in cancer tissues predicts poor prognosis of lung cancer patients." (PMID 33976738, 2021). "The top 5 long non-coding RNAs that use the IPCARF algorithm to predict lung cancer are: GAS5,XIST,CDKN2B-AS1, PVT1 and HOTAIR." (PMID 33794766, 2021). "By reducing miRNA-21 expression, lncRNA GAS5 induces apoptosis in lung cancer cells exposed to radiotherapy." (PMID 33670518, 2021). "It is noteworthy that lncRNA GAS5 can regulate the response of lung cancer cells to chemotherapy via modulating the miRNA/PTEN axis." (PMID 33670518, 2021). "Another tumor-suppressive lncRNA GAS5 (growth arrest-specific transcript 5) inhibits tumor formation in lung cancer by negatively regulating miR-205 expression, and thus, increasing PTEN expression." (PMID 33412752, 2020).
lung carcinoma (continued). "It has been shown that the lncRNA GAS5 plays a tumor suppressor activity in lung cancer by sponging miRNAs with oncogenic properties." (PMID 32111002, 2020). "For example, GAS5 has been proven to be a potential therapeutic target for lung cancer by inhibiting angiogenesis." (PMID 33072553, 2020). "To summarize, exosomal GAS5 represses HUVECs proliferation and enhances their apoptosis, thus, inhibiting angiogenesis in lung cancer." (PMID 32924276, 2020). "LncRNAs such as lnc ADAMTS9-AS2, MT1JP, and GAS5 act as tumor suppressors in lung cancer through lncRNA/miRNA ceRNA networks, which regulate the expressions of well-known tumor suppressors such as PTEN and TIMP2." (PMID 33412752, 2020). "Remarkably, lung cancers treated with GAS5-siRNA showed an expected reduction in GAS5 expression, independent of SNORD78 levels that remain unchanged." (PMID 32111002, 2020). "Lung cancer-derived exosomal GAS5 regulates the apoptosis, proliferation, and tube formation of human umbilical vein endothelial cells (HUVECs)." (PMID 33072553, 2020). "Otherwise, circulating GAS5 is repeatedly suggested as a marker for the detection of lung cancer, showing a consistent down-regulation in cancer patients." (PMID 32435497, 2020). "A recent study reported that GAS5 is down-regulated in lung cancer cells and at the same time, its knockdown increased cis-platin IC50 in an in vitro system, while its overexpression decreased it." (PMID 33076450, 2020). "The results showed that, at week 12, GAS5 levels in serum exosomes from urethane-induced lung cancer mice were significantly lower than those in the control group." (PMID 31186629, 2019). "We found that PTEN mRNA was significantly reduced in human lung cancer tissue samples and was positively correlated with GAS5 expression." (PMID 31186629, 2019). "We also detected GAS5 levels in cell culture supernatant exosomes and found that exosomes from A549, H1299, and 95D lung cancer cells contained lower GAS5 level than normal 16HBE lung cells." (PMID 31186629, 2019). "We then treated HUVECs with these exosomes and found that exosomes from lung cancer cells with higher GAS5 content inhibited HUVECs proliferation and tube formation and promoted HUVECs apoptosis." (PMID 31186629, 2019). "Of note, GAS5 was significantly reduced in the serum exosomes from urethane-induced lung cancer mice and lung cancer tissues compared with control samples." (PMID 31186629, 2019). "And the exosomes of lung cancer cells containing high GAS5 level inhibited HUVECs proliferation and tube formation and increased their apoptosis." (PMID 31186629, 2019). "The results showed GAS5 expression in lung cancer tissues of urethane-treated mice was significantly lower than that in normal lung tissues." (PMID 31186629, 2019). "GAS5 was expressed at low levels in lung cancer tissues and cell lines, which was consistent with the current literature." (PMID 31186629, 2019). "The results showed that in 30 pairs of matched lung cancer samples (cancerous vs. adjacent normal tissues), there were 25 cases showing lower GAS5 expression in cancer tissues than adjacent normal tissues." (PMID 31186629, 2019). "GAS5 expression was next detected by qPCR in human lung cancer tissues, the lung cancer cell lines (A549, H1299, 95D), and normal bronchial epithelial cells (16HBE)." (PMID 31186629, 2019). "In conclusion, we reported, for the first time, that exosomal GAS5 participates in lung cancer angiogenesis." (PMID 31186629, 2019). "After overexpressing GAS5 in the lung cancer cell lines A549, H1299, and 95D, GAS5 levels were significantly increased." (PMID 31186629, 2019). "Based on ROC curve analysis results, the accuracy of GAS5 expression levels for lung cancer diagnosis is good." (PMID 30866866, 2019). "As another example, lncRNA growth arrest specific 5 (GAS5) has been identified to be downregulated in lung cancer tissues compared with in adjacent normal tissues." (PMID 31516584, 2019).
lung carcinoma (continued). "Our results support the potential of exosomal GAS5 to be a new target for inhibiting lung cancer angiogenesis." (PMID 31186629, 2019). "Our study found that lung cancer-derived exosomal GAS5 affected the proliferation, apoptosis, and tube formation of HUVECs." (PMID 31186629, 2019). "And there was a significant positive correlation between GAS5 expression in serum exosomes and lung cancer tissues." (PMID 31186629, 2019). "The current literature reports that GAS5 is an important molecule for the proliferation, apoptosis, invasion, metastasis, and angiogenesis of lung cancer." (PMID 31186629, 2019). "Multiple lncRNAs were confirmed to be involved in the context of lung cancer, including lncRNA growth arrest-specific 5 (GAS5)." (PMID 29367413, 2018). "Recent reports had showed that many of the lncRNAs, including H19, HOTAIR, MALAT1, ANRIL, GAS5, and GAS5-AS1, were tumor-associated, especially in lung cancers." (PMID 30154938, 2018). "The expression levels of lncRNA GAS5 in lung cancer tissues were significantly lower than those in the corresponding normal tissues (P<0.01)." (PMID 29207621, 2017). "Real-time PCR analysis found that the expression levels of lncRNA GAS5 in lung cancer tissues were significantly lower than those in the corresponding normal tissues (P<0.01)." (PMID 29207621, 2017). "Next, we further examined the expression of GAS5 in lung cancer and adjacent tissue samples with different genotypes." (PMID 29207621, 2017). "Several known lung cancer-associated lncRNAs, such as HOTAIR, GAS5, PVT1, and UCA1 were found in this top list which further supported the power of this analysis." (PMID 26862852, 2016). "As a tumor suppressor, exosomal lncRNA growth arrest-specific transcript 5 (GAS5) was found to be downregulated in patients with early-stage lung cancer compared to healthy individuals, and they were found even lower in patients with advanced lung cancer." (PMID 41227214, 2025). "studies have shown that the level of lncRNA GAS5 (growth arrest‐specific 5) is not only low in lung cancer tissues and serum exosomes, but also significantly lower in lung cancer cells (A549, H1299 and 95D) and their exosomes than that of normal bronchial epithelial cells." (PMID 39247621, 2024). "Additionally, lung cancer‐derived exosomal GAS5 (exo‐GAS5) affects the apoptosis, proliferation, and tube formation of HUVECs." (PMID 39247621, 2024). "Lastly, roles for GAS5 in sensitizing lung cancer cells to radiotherapy have also been reported." (PMID 37370745, 2023). "Exosomes containing high levels of GAS5 stimulate apoptosis in lung cancer and impair its growth." (PMID 35765040, 2022). "The lncRNA GAS5 is thought to suppress lung cancer progression." (PMID 35765040, 2022). "Therefore, the transcription level of GAS5 can be regulated through the application of new targeted drugs or combination therapy to improve the prognosis of lung cancer patients." (PMID 33976738, 2021). "Furthermore, GAS5 expression of different lung cancer cell lines (H-460, H-129 and A-549) was evaluated, respectively." (PMID 33976738, 2021). "Whether the change of GAS5 expression could affect the chemotherapy sensitivity of lung cancer cells using three common chemotherapeutic molecular drugs was also observed." (PMID 33976738, 2021). "Meanwhile, LncRNAs such as GAS5, TP53TG1, and AC078883.3 have been associated with cisplatin sensitivity through miR‐21/PTEN, miR‐18a/PTEN, and PTEN/AKT axis, respectively, in human lung carcinomas." (PMID 33433063, 2021). "Also, GAS5 was decreased in human lung cancer tissues, lung cancer cells, and in cell line-derived exosomes." (PMID 34830787, 2021). "In this study, we aimed to clarify the correlation between GAS5 and lung cancer cells." (PMID 33976738, 2021).
lung carcinoma (continued). "Subsequently, they analyzed levels of GAS5 in A549, H1299, and 95D lung cancer cells and normal 16HBE lung cells demonstrating that GAS5 was downregulated in cancer cells, and cells with overexpressed GAS5 resulted in inhibition of cancer proliferation and increased apoptosis." (PMID 33224198, 2020). "Interestingly, the individual role of SNORD78 in lung cancer is supported by the opposite effect of its host Growth Arrest Specific 5 (GAS5) gene." (PMID 32111002, 2020). "Furthermore, the GAS5 expression level in tumor-derived exosomes correlates with tube formations as exosomes of lung cancer cells having low GAS5 expression promoting tube formation and vice versa." (PMID 32992718, 2020). "In lung cancer, lower expression of lncRNA GAS5 in the exosomes promotes tumor angiogenesis." (PMID 33006432, 2020). "The important functions of GAS5 in lung cancer have been identified in several studies." (PMID 31186629, 2019). "Moreover, exosomal GAS5 levels and GAS5 expression in lung cancer tissues were positively correlated." (PMID 31186629, 2019). "In addition, exosomes derived from lung cancer cells overexpressing GAS5 suppressed cell proliferation and tube formation in HUVECs, in contrast to exosomes from the negative control group." (PMID 31728212, 2019). "Our study supports the importance of exosomal GAS5 in lung cancer." (PMID 31186629, 2019). "GAS5 overexpression in lung cancer cells increased GAS5 level in cell culture supernatant exosomes." (PMID 31186629, 2019). "Overall, our results suggest that exosomal GAS5 could be a new therapeutic target for lung cancer which inhibits angiogenesis." (PMID 31186629, 2019). "Furthermore, GAS5 was lowly expressed in human lung cancer tissues, lung cancer cells, and cells culture supernatant exosomes." (PMID 31186629, 2019). "GAS5 expression in normal lung tissue and lung cancer tissue was also detected by qPCR." (PMID 31186629, 2019). "We further detected GAS5 expression in human lung cancer tissue samples and lung cancer cell lines." (PMID 31186629, 2019). "Therefore, we first used lentiviral-mediated GAS5 overexpression in lung cancer cells and then collected exosomes from cell culture supernatant." (PMID 31186629, 2019). "A study from 2015 reported that a decreased lncRNA GAS5 expression was associated and/or involved in the lack of resistance capacity when lung cancer was exposed to gefitinib-based therapy." (PMID 28904641, 2017). "The study identified a decreased GAS5 expression in lung AD tissues and in lung AD cells A549, and H1299 EGFR-wild-type, as well as EGFR-mutated H1975 (T790 M) and HCC827 (E746-A750 deletion) lung cancer cell lines." (PMID 28904641, 2017). "Several characterized cancer-associated lncRNAs were identified, such as PVT1, TINCR, and GAS5; while the well-known lung cancer-associated lncRNA, MALAT1 was not included." (PMID 26918601, 2016). "In addition, the GAS5 transcript levels were found to be significantly reduced in breast and lung cancer samples compared with adjacent unaffected normal tissues." (PMID 25925741, 2015). "Therefore, it was interesting that whether GAS5 could be the bridge factor between HG and lung cancer." (PMID 29367413, 2018). "It has been recognized that lncRNA growth arrest-specific 5 (GAS5) participates in multiple lung disorders, such as asthma and lung cancer." (PMID 36918759, 2023). "LncRNAs have become the key regulatory factors in development and progression of lung cancer, functioning as oncogenes (e.g., MALAT1, HOTAIR, H19 and ANRIL) or tumor suppressors (e.g., MEG3, GAS5, and TUG1)." (PMID 34976181, 2022). "Additionally, the SNPs at 22q12 and the 15q15.2 locus would increase the risk of lung cancer even in non-smokers; maybe the GAS5 SNP rs145204276 Ins/Del + Del/Del owns a similar effect to them." (PMID 36011604, 2022). "However, the influence of GAS5 on lung cancer and the specific mechanism remain unclear." (PMID 33976738, 2021).
lung carcinoma (continued). "Differential expression patterns and levels of the LncRNA SOX2‐OT, in contrast to other LncRNAs (GLI1‐AS, GAS5, ZEB1‐AS and UCA1), were identified in several lung cancer cell lines at baseline cellular culture conditions." (PMID 33433063, 2021). "We have demonstrated using in vitro cisplatin or TKI‐erlotinib treatment, routinely used in human lung cancer therapy schemes, a significant induced overexpressed LncRNA SOX2‐OT level, in contrast with other LncRNAs, such as GLI1‐AS, GAS5, ZEB1‐AS, and UCA1." (PMID 33433063, 2021). "For long non-coding RNAs, HOTAIR, LINC00152, growth arrest-specific transcript 5 (GAS5), lncRNA-NEF, and SOX2 overlapping transcript (SOX2OT) have been identified as potential biomarkers for lung cancers." (PMID 32316322, 2020). "In this study, lung cancer in mice was induced by urethane; we found that growth arrest specific 5 (GAS5) was lowly expressed in the serum exosomes and lung cancer tissues of mice with lung cancer." (PMID 31186629, 2019). "To date, only a few lncRNAs (including MALAT1, HOTAIR, H19, MEG3, GAS5, ANRIL, and SOX2OT etc.)have been reported to be dysregulated and functionally characterized in lung cancer and most of the studies were based on microarray expression data." (PMID 26862852, 2016). "GAS5 competitively binds to miRNA-29-3p with phosphatase and tensin homolog (PTEN) in HUVECs to upregulate the PTEN expression and inhibit the phosphorylation of PI3K/AKT, suggesting GAS5 plays an important role in lung cancer angiogenesis." (PMID 31186629, 2019). "Overexpression of GAS5 could enhance the inhibitory effect of Gefitinib on EGFR phosphorylation and its downstream signaling activation, while enhancing the sensitivity of lung cancer cells to EGFR-TKI." (PMID 31750253, 2019). "Lung cancer cells transfected with GAS5 overexpression vectors released higher levels of exosomal GAS5 than the negative control group." (PMID 31728212, 2019). "In eight metastatic lung cancer tissues, GAS5 expression was also lower than that in the normal specimens, but not significantly (P = 0.087)." (PMID 25925741, 2015). "Our current results also show a lower GAS5 expression in metastatic lung cancer tissues, although this difference was not statistically significant, possibly because of the limited number of cases analyzed." (PMID 25925741, 2015). "Another lncRNA, growth arrest-specific 5 (GAS5), may affect various respiratory diseases, including lung cancer, asthma, and fibrosis; however, there is no study on its mechanisms of action and involvement in CS-caused airway remodeling." (PMID 35880572, 2022). "This evidence suggests that GAS5 is an important regulator promoting the proinflammatory and anti-tumorigenic macrophage activation within the TME and that targeting GAS5 could serve as an option for lung cancer treatment." (PMID 34439281, 2021). "GAS5 could influence invasion and metastasis of lung cancer through EMT process, which shed light on the prospect for development as a therapeutic target for lung cancer." (PMID 33976738, 2021).